MYC (MYC proto-oncogene, bHLH transcription factor)
Diseases named in the same sentence as MYC in open-access papers (continued):
Sharing a sentence is not in itself a finding about the gene and the disease.
tumor (continued). "In the MDA-MB-231 breast cancer cell line-derived xenograft model, EN4 decreased MYC-MAX DNA binding, resulting in compromised cell proliferation and tumor growth in vivo." (PMID 40290126, 2025). "These MYC-regulated substrate increase in TCA cycle and metabolic pathways provide energy for cells, promoting tumor cell proliferation." (PMID 40303483, 2025). "DNA methylation analysis classified the tumor within the SP-EPN-MYCN subgroup, indicating the shared function between MYC and MYCN." (PMID 40365336, 2025). "To avoid the potentially toxic effects of the combination administration of 10058‐F4 and Bobcat339 on mice, we stably knocked down MYC, TET3 alone or in combination in TMEM65‐overexpressing MDA‐231 cells and then carried out mouse xenograft tumor assays." (PMID 40546127, 2025). "Given the central role of MYC in cancer, this work provides mechanistic insight into how cancer cells may sustain protein biosynthesis under nutrient-limiting conditions, with implications for understanding tumor growth and therapeutic resistance in metabolically stressed microenvironments." (PMID 40524273, 2025). "In mutant HEC‐1‐A cell‐derived tumours with generally decreased expression levels of the glycolytic pathway and PPP, MYC mRNA levels were also slightly reduced in comparison with their wild‐type counterparts." (PMID 40186514, 2025). "This aberrant signaling further promotes activation of downstream pathways such as RAS, ERK, and MYC/TGF-β1, contributing to tumor growth and immune evasion." (PMID 40943058, 2025). "Conventional double-color FISH confirmed that all tumor cells carried gene rearrangements of BCL2 and MYC." (PMID 41142614, 2025). "MYC subsequently promotes expression of glycolytic genes like LDHA, markedly increasing lactate production and glucose uptake, thereby accelerating tumor cell proliferation and invasion." (PMID 41020873, 2025). "MYC is involved in EMT function, and angiogenesis has been shown to link EMT-induced cancer stemness to tumor initiation." (PMID 39256881, 2024). "The copy numbers of shared CNVs, such as PDGFRA/KIT, CDK4, MYC, KRAS, and VEGFR2, were highly consistent (Pearson correlation = 0.95, P = 0) between the CSF and tumor tissues." (PMID 38388726, 2024). "Analysis by ML models and methods confirmed the findings that the addition of both stromal FOXC1 and tumor pERK1‐2 to established factors of prognosis (NCCN‐IPI, cell of origin, and MYC/BCL2 double expression) improved C‐index." (PMID 39404228, 2024). "MYC, EGFR and KIT are among such genes with late gains in both OS and BRCA, emphasizing their ability in stimulating cell multiplication in multiple tumor types." (PMID 38448455, 2024). "In part at least, the tumour suppressive role of FBXW7 has been ascribed to its ability to drive the ubiquitination and degradation of oncoproteins including c‐MYC, NOTCH, c‐JUN, Cyclin E and MCL1, as well as pro‐aneuploidy factors such as Aurora A." (PMID 37866880, 2024). "Apart from NCAPD3 regulation of STAT3, we also reported before that NCAPD3 upregulated other TFs like MYC and EZH2 to promote tumor progression." (PMID 38561330, 2024). "Altogether our findings indicate that MYC overexpression and MAPK/ERK pathway activation in cancer cells drives a tumor-permissive, myeloid-enriched TME in both preclinical and human HCC." (PMID 38519484, 2024).
tumor (continued). "The aim of the study was to investigate the methylation status of CDKN1, CDKN2A, MYC, Smad3, SP1, and UBC genes in tumor tissue (control-normal tissue) in 50 patients (37 men and 13 women) with HPV-negative HNSCC." (PMID 38540340, 2024). "In the context of cancer, eIF5A hypusination facilitates translation elongation of MYC and regulates the focal adhesion kinase PEAK1, both of which contribute to tumor growth." (PMID 38689086, 2024). "MYC-overexpressing TNBC cells rely heavily on FAO for their energy needs, and the inhibition of FAO significantly impairs tumor growth and survival." (PMID 39408832, 2024). "We selected three genes known to modulate tumor immunogenicity (IFNGR2, STAT1 and MYC) for which 2 sgRNA pools were produced." (PMID 39497819, 2024). "MYC, CD47 and PD-L1 are considered to generate an immunosuppressive “cold” tumor microenvironment in CRC, providing insight into why LINC00460 induces immune escape and the shaping of suppressive tumor immune microenvironment." (PMID 39135122, 2024). "These cells rely on expression of stem cell transcription factor genes including SOX2, MYC, and NANOG to generate tumor spheres in vitro and tumors in vivo with high frequency." (PMID 38886396, 2024). "The aim of the study was to evaluate promoter methylation of CDKN1, CDKN2A, MYC, Smad3, SP1, and UBC genes in tumor tissue of HNSCC patients." (PMID 38540340, 2024). "The IHC study of c-MYC and CDKN2B in canine TVTs found that most of the staining was focal and confined to the cytoplasm of tumor cells (Figure-3a)." (PMID 39185058, 2024). "The MYC activator MYB was identified as a target of miR-103, which is a tumor suppressor downregulated in ALL." (PMID 38835346, 2024). "With co-operation with c-MYC, the MYBL1 gene can rescue human B-cell neoplasia from apoptosis, aiding in tumor progression." (PMID 39796135, 2024). "The key concept emerging from our data is that MYC finely coordinated two metabolic processes that act in parallel, the NOX4-ROS pathway and the PLK1-NUDT1 nucleotide-sanitizing pathway, to maintain tumor cell survival." (PMID 38493213, 2024). "The first striking feature is the adaptation of similar transcriptional metaprograms (Cycling, MYC, EMT, Stress) in the respective tumor cell and TME compartments." (PMID 39362842, 2024). "Additinally, the knockdown of KLF4 in the SW480 CRC cell line induced the YAP pathway and its downstream genes, including EGFR, MYC, BIRC5, and CTGF, leading to tumor proliferation." (PMID 38167453, 2024). "MYC is highly relevant to EMT, a process that contributes to various aspects of tumor progression, including cell motility and metastasis." (PMID 38753413, 2024). "High-AIDAS tumors frequently exhibit amplification of known oncogenes, such as MYC, and deletions in tumor suppressor genes, linking AIDAS with oncogenic pathways that drive tumor progression and therapeutic resistance." (PMID 39650663, 2024). "Concurrently, genes correlated with invasiveness and metabolic activity, such as E2F Targets, MYC Targets V1, and PI3K AKT MTOR Signaling, were upregulated within the tumor cells of the solid pattern samples." (PMID 38505588, 2024). "For example, lncRNA-MIF (MYC inhibitory factor), acts as a tumor suppressor to dampen MYC expression in CRC and other cancers, in turn inhibiting aerobic glycolysis and tumorigenesis enacted through MYC." (PMID 39075086, 2024). "Induced by estrogen signaling in a MYC-dependent manner, cell polarity proteins Scribble (SCRIB) has tumor-promoting function and mediates tumor cell proliferation and endocrine resistance to tamoxifen in ER-positive breast cancer cells." (PMID 38705513, 2024). "The overexpression of MYC induces the expression of CD47 and PD-L1 in tumor cells, allowing them to evade immune surveillance." (PMID 38280005, 2024).
tumor (continued). "Given this selective dependency of G148 on MYC overexpression, we argued that being able to predict the formation of gene-activating E-P neoloops on a patient-specific basis could inform treatment options, as such neoloops are selected during tumor development and could represent new dependencies." (PMID 38724522, 2024). "NUT‐fusion proteins drive the formation of hyperacetylated chromatin “megadomains” or “superenhancers,” including the enhancer regions of genes such as MYC and TP63, which inevitably promote tumor growth and prevent differentiation." (PMID 40336973, 2024). "Neural-like tumor cells had the strongest expression of TNF and MYC signaling, and intermediate cells had the strongest interferon signaling." (PMID 39417106, 2024). "Kon and colleagues discovered that CMA had a tumor-suppressive effect on MEF cells, promoting proteasomal degradation and inhibiting MYC oncogenic activity." (PMID 37450923, 2024). "Several genes from multiple families have been identified as possible biomarkers for disease, including those from the MYC and ETS families, as well as several tumour suppressor genes, Androgen Receptor signalling genes and DNA repair genes." (PMID 39410867, 2024). "Inhibiting Exportin-1 (XPO1) in vivo induces marked tumor regression in an autochthonous MYC-transgenic HCC model and inhibits tumor growth in HCC patient-derived xenografts." (PMID 38302473, 2024). "The activity of c-MYC is controlled via complex mechanisms which include many c-MYC binding proteins, including prefoldin-5 (PFDN5) which has been proposed as a tumor suppressor." (PMID 38397067, 2024). "We further examined the anti‐tumor effect of DU101 and DU102 in our previously used liver CSC transgenic mouse model, Axin2‐CreER driven MYC‐ON liver tumor mouse model." (PMID 39225354, 2024). "This study explored how DNA methylation in CTVT gene promoters, particularly MYC (oncogenic) and CDKN2B (tumor suppressor), affects gene and protein expression." (PMID 39185058, 2024). "Tumours driven by MYC, KRASG12D, and BRAFV600E all show increased basal NRF2 transcriptional activity promoting tumour survival." (PMID 38434478, 2024). "In conclusion, we found NCAPD3 inhibited miR-30a-5p expression to promote cell proliferation and migration and accelerate tumor growth through MALAT1 as a sponge and MYC transcriptional repression pathways." (PMID 38561330, 2024). "Within protective tumor niches, CLL cells display heightened activation of BCR, TLR, NFκB, E2F, and MYC signaling to sustain survival and proliferation." (PMID 38687198, 2024). "Oncogenes and tumor suppressors: Some oncogenes, such as the ones seen in KRAS or MYC, help increase the level of HIF-1α, thereby contributing to tumor development." (PMID 39493156, 2024). "In line with this idea, numerous studies regarding FAM46C have indeed found anti-correlation between FAM46C and MYC expression, suggesting that the tumour suppressor effect of FAM46C relies, at least in part, on inhibiting MYC." (PMID 38730656, 2024). "In this way, MYC promotes GSH synthesis de novo, and then finally resists oxidant to promote tumor progression." (PMID 38218942, 2024). "The metabolic sensor and stress redox checkpoint, AMPK, is required for c-MYC-mediated survival under stress conditions, as AMPK has a tumor-protective role in MYC-driven cancer." (PMID 37450923, 2024). "A comparison of EGR1, FOS, IER2, JUN, KLF6, MYC, and FOSL2 gene expression in 481 tumor samples revealed that individual tumors vary substantially in the expression of all analyzed genes." (PMID 39436655, 2024).
tumor (continued). "The Notch signaling pathway and MYC targets play broad roles in the promotion or inhibition of proliferation and cell death, related to the regulatory role of SENP2 in tumor growth." (PMID 38957470, 2024). "Some targets, such as DLX4, NDRG3, WNT1, MYC, CREB1, and SIRT6, are involved in tumor or cell proliferation." (PMID 39618816, 2024). "Clearly, c-MYC plays a complex role in the tumor microenvironment of GBM.c-MYC is dysregulated in 70% of tumors, and targeting the dysregulated MYC protein plays abroad therapeutic role." (PMID 38716541, 2024). "MYC is one of the most common and well-studied pan-cancer oncogenes, while FAM46C is now becoming a well-established pan-cancer tumour suppressor, making this anti-correlation really attractive and exploitable for future therapy implementation." (PMID 38730656, 2024). "Our findings revealed that the TFs E2F1, HMGA1, MYC, FOSL1 and CREB3 exhibited exceptional levels of activity within C2 UBE2C+ tumour cells." (PMID 38894657, 2024). "Amino acids act as pivotal signaling molecules, stimulating signal pathways like mTORC1, MYC and KRAS to drive tumor growth and proliferation." (PMID 38218942, 2024). "While targeting MYC in TNBC is an area of active research, targeting transcription provides a means to simultaneously target MYC as well as other oncogenic drivers of TNBC, thereby circumventing the problem of patient and tumour heterogeneity." (PMID 38001268, 2024). "Besides, PVT1 may contribute to tumor development independently of MYC." (PMID 38994720, 2024). "The results showed that BAMBI was positively correlated with tumor proliferation, EMT markers, MYC targets, and cellular response to hypoxia in HCC; it was negatively correlated with glycolysis/gluconeogenesis and fatty acid degradation pathways." (PMID 39684424, 2024). "The enrichment of transcription factors MYC and TAF7 in cluster 0, along with pathway enrichment analysis, revealed the activation of the MAPK pathway in these FABP6+ tumor cells." (PMID 38277205, 2024). "Further, MYC forms a transcriptional complex with SKp2, MIZI, and p300 to induce tumor migration and metastasis via RhoA activation." (PMID 37450923, 2024). "The resulting subset of tumors follow distinct evolutionary paths compared with WNT/MYC-driven LGR5-derived tumorigenesis, and are characterized by an inflammatory tumor phenotype more prone to infiltration from the TME." (PMID 38902475, 2024). "Primarily recognised as a tumour suppressor, FOXO1 exerts its tumour‐suppressive influence by regulating downstream PI3K/AKT signalling and attenuating the activities of the MYC and WNT signalling pathways." (PMID 38899748, 2024). "As JHU083 is known to affect c-MYC and HIF-1α signaling, we investigated c-MYC and HIF-1α expression levels in MB49 tumor/stromal cells." (PMID 38701369, 2024). "Collectively, MYC promotes serine synthesis and thereby GSH and NADPH production to resist oxidation and promote tumor growth." (PMID 38218942, 2024). "Further analysis revealed that BAMBI was strongly correlated with tumor proliferation, EMT markers, MYC targets, cellular response to hypoxia, glycolysis/gluconeogenesis, fatty acid degradation pathways, as well as regulating immune checkpoints in HCC." (PMID 39684424, 2024). "The results showed the expression of tumor malignant characteristic genes such as CDKN2A CKS1B, HSPA9, IDH2, and MYC among different subpopulations of plasma cells, with high expression in plasma cell_2." (PMID 39271659, 2024).
tumor (continued). "Recent studies have found that the AKT signaling pathway is closely related to tumor metabolism, and AKT can promote tumor cell glycolysis by activating MYC." (PMID 38822351, 2024). "Given their hyperactivation-promoting tumor abilities, the hsa-miR-1225-5p interaction targets LASP1, PEG10, and MYC that were chosen from curated open data have been thoroughly examined in tumor models with meaningful participation." (PMID 38204280, 2024). "We further showed that the two downstream effects of BETi - MYC repression and AKT inhibition - simultaneously target p21 for the protein expression and nuclear translocation, facilitating its tumor suppressive actions." (PMID 38617536, 2024). "MYC, EZH2 and CTNNB1 were the primary stemness genes with high expression levels in C2 UBE2C+ tumour cells." (PMID 38894657, 2024). "The low expression of MYC in HNSCC induces DNA damage related cGAS-STING pathway, which increases the recruitment of chemokines by CD8 T cells, promotes tumor immune response, and inhibits the proliferation and migration of HNSCC." (PMID 39403369, 2024). "The MYC activator TCF4, which is part of the β-catenin complex that induces EMT and tumor invasion, was a top synthetic lethal hit with both GPS167 and 1C8." (PMID 38753413, 2024). "Our method applies a technique called attention-based multiple instance learning to regress the proportion of c-MYC-positive and BCL2-positive tumor cells from pathologist-scored tissue microarray cores." (PMID 38243330, 2024). "Each cell was scored using the HALLMARKER50 gene set, and the results showed that the MYC, oxidative stress, and angiogenesis pathways had higher scores in most cell types, suggesting that these cell types may have been reprogrammed in the tumor microenvironment." (PMID 39720182, 2024). "MYBL1, VCPIP1, MYC and BOP1 transcript expression levels were assessed in MCF10A non-tumor triple negative cell lines compared to Hs 578T, BT-549 and MDA-MB-231 TNBC cell lines." (PMID 38473786, 2024). "More importantly, small and colocalized condensates formed by endogenous KLF16 and MYC were observed through super-resolution imaging in BLCA cell lines and tumor tissues." (PMID 39551759, 2024). "Apoptosis signalling, MYC-mediated apoptosis signalling and PTEN signalling can all be classified as tumour suppressor pathways since they prevent tumour formation." (PMID 39179604, 2024). "Several tumor hallmarks, such as mTORC1, PI3K-AKT-mTOR and KRAS, were activated in MPC3, and other tumor biological processes, including hypoxia, peroxisomes, MYC targets and oxidative phosphorylation, were upregulated in MPC3." (PMID 38486026, 2024). "We concluded that patients with PDAC with elevated MYC expression also overexpress RUVBL1, and that tumours with the highest expression of both proteins are the most aggressive." (PMID 38821858, 2024). "Targeting this loop with bromodomain inhibitors, such as OTX015 and ABBV-744, suppressed the transcription of both KLF16 and MYC, resulting in reduced BLCA cell viability and tumor growth, as well as increased sensitivity to chemotherapy." (PMID 39551759, 2024). "It was reported that METTL3 regulates HDGF in an m6A-mediated manner to promote tumor angiogenesis and glycolysis and also regulates ZMYM1, SPHK2, and MYC to promote GC tumor metastasis." (PMID 39195675, 2024). "This hindered transcription factor access and downstream activation of the oncogenic transcriptional programs regulated by AR, FOXA1, ERG, and MYC and led to inhibition of CRPC tumor growth." (PMID 38586029, 2024). "In this work, we discovered that MYC orchestrated the crosstalk of two parallel metabolic pathways, the NOX4-ROS pathway and the PLK1-NUDT1 nucleotide-sanitizing pathway, to promote tumor cell survival." (PMID 38493213, 2024).